IL7R (interleukin 7 receptor)
Diseases named in the same sentence as IL7R in open-access papers (continued):
Sharing a sentence is not in itself a finding about the gene and the disease.
tumor (continued). "However, the population of IL-7R+ CD8+ T cells accounted for over 90% of tumor-specific CD8+ T cells in lymph nodes in conditions associated with functional memory." (PMID 37459511, 2023). ">95% of tumor-specific T cells expressed high levels of IL-7R." (PMID 37459511, 2023). "Stimulation of the memory T-cell compartments appears to be of importance for the reported anti-tumor activities of IL-7R agonists, either administered to animals or patients; or treatment of engineered T-cells undergoing ex vivo expansion prior to transfer to patients." (PMID 37874823, 2023). "Strikingly, we found that IL-7R was highly expressed on the surface of tumor-specific CD8+ T cells (IL-7Rhi) in functional memory, but not on tetramer-negative CD8+ T cells (IL-7Rlo) in this setting, making it unique in this aspect from other canonical markers of memory that were evaluated." (PMID 37459511, 2023). "IL-7R can mediate potential tumor-promoting functions in solid cancers." (PMID 37221625, 2023). "These CD27-based T2-CAR T cells demonstrated a higher survival rate in the spleens and tumor tissues of tumor-bearing mice and exhibited upregulated IL-7Rα expression and downregulated PD-1 expression, indicating a multifaceted mechanism of enhanced killing effect." (PMID 37954074, 2023). "Whether this high IL-7R expression was marking a tumor-specific CD8+ population became important to address." (PMID 37459511, 2023). "Notably, in the present study, the expression levels of αSMA and FAP, known as CAF markers, were positively correlated with the expression of IL-7R in ESCC tumor nests." (PMID 36672342, 2023). "Importantly, greater than 95% of tumor-specific T cells in draining lymph nodes after therapy express high levels of IL-7R." (PMID 37459511, 2023). "The population of PD-1- / KLRG-1- / IL-7Rα+ cells may correspond to a bystander naïve CD8 T cell population migrating to the tumor attracted by the inflammatory environment of the tumor." (PMID 37033927, 2023). "We also investigated the relationship between IL-7R expression and tumor stage." (PMID 35159120, 2022). "IL-7/IL-7R have dual roles in the development of cancer, and exploring the IL-7R-mediated signaling pathways has shown good therapeutic effects in both liquid tumors and some solid tumor models, indicating a promising future for inhibiting tumor occurrence." (PMID 36142322, 2022). "Moreover, several publications have described an autocrine action of the IL‐7/IL‐7R pathway on tumor cells to promote cell proliferation." (PMID 36054746, 2022). "A subpopulation of tumor-specific keratinocytes (TSKs) showed significant epithelial-mesenchymal transition (EMT) features in recurrent cSCC, probably due to their active communication with IL7R+ cancer-associated fibroblasts (CAFs)." (PMID 36438481, 2022). "It has been postulated that IL-7/IL-7R signaling may promote tumor growth by two separate signaling pathways, angiogenesis and the upregulation of Tregs, thereby decreasing cytotoxic T-cell activity." (PMID 36139575, 2022). "IL-7R, mTOR and tumor stage are the strongest predictor of survival." (PMID 35778432, 2022). "Collagen and tenascin C (TNC) can promote EMT in tumors 64, 65; therefore, the interaction between TSKs and IL7R+ CAFs may mediate the EMT of tumor cells in recurrent cSCC." (PMID 36438481, 2022). "Additional correlation analyses showed that IL7R expression was significantly associated with markers of cells involved in immunosuppression such as CD68, CD163, MRC1, and IL10 (tumor‐associated macrophages), CD4, FOXP3 (regulator T lymphocytes) and CD274 (PD‐L1)." (PMID 36054746, 2022).
tumor (continued). "The anti-IL-7R antibody-drug conjugate (A7R-ADC) has an anti-tumor effect on lymphatic malignancies and can target steroid-sensitive and -resistant cells; therefore, A7R-ADC could be a hopeful new choice for cancer treatment." (PMID 36142322, 2022). "IL-7R, mTOR and tumor stage were the strongest predictors of survival." (PMID 35778432, 2022). "In the TCGA dataset, IL‐7R gene expression was measured by RNASeq and represents the sum of both tumor cells and infiltrating cell expression, whereas the immunohistological method evaluated IL‐7R protein expression on tumor cells." (PMID 36054746, 2022). "Moreover, IL-7R expressing effector memory T cells derived from naive T cells possess high affinity to IL-2 and thereby enhance the survival of themselves in tumor microenvironment." (PMID 34575268, 2021). "In similar to tissue-resident CD103+IL-7R+ Tregs, these amplified effector memory T cells population (CCR7-CD45RA-CD3+IL-7R+) may contribute to constitute immunosuppressive environment in early onset of tumor formation." (PMID 34575268, 2021). "iAMP21 tumours were characterised by excess RB1 deletion (40%) and IL7R mutation (20%)." (PMID 34753926, 2021). "On the other hand, IL-7/IL-7R improves chemotherapeutic sensitivity and anti-tumor immunity." (PMID 35069695, 2021). "However, there is few data for elucidation of IL-7R level in blood cells and tumor cells from tumor patients." (PMID 34575268, 2021). "Notably, LINC01857 and LINC02446 were the shared competing lncRNA of both IL2RA and IL7R, supportive of their significant involvement in tumor progression." (PMID 34159752, 2021). "Increased frequencies of IL-7Rα expressing tumor antigen-specific CTLs found in the present study could indicate increased survival and persistence of memory CTLs in the tumor microenvironment and possibly providing long-term therapeutic benefit to ICT." (PMID 33262762, 2020). "The expression of IL-7 and its receptor IL-7R in tumor tissues was also recovered by TCM." (PMID 31138762, 2019). "Decreased IL-7 concentration around the tumor might be an additional effect of the impaired IL-7/IL-7R signaling mechanism of cancer-induced immunosuppression." (PMID 31185636, 2019). "We determined whether tumor cell migration and invasion are specific for IL-7 and analyzed IL-7R signaling and epithelial–mesenchymal transition (EMT)-related molecules." (PMID 31061414, 2019). "The results of IL-7 and IL-7R levels in tumor tissues showed the similar trends as that in serum." (PMID 31138762, 2019). "Moreover, the expressions of IL-7 and its receptor IL-7R in tumor tissues were also determined by Western blot assay." (PMID 31138762, 2019). "Interestingly, the expression of IL‐7R was induced by the treatment of cisplatin, and IL‐7 combined with cisplatin significantly decreased the expression of IL‐7R in tumour tissues." (PMID 31599032, 2019). "The results showed that the inhibition of Lnc-IL7R could effectively inhibit tumor growth, which might be related to decreased expression of Lnc-IL7R." (PMID 29720427, 2018). "We found that the administration of siRNA for Lnc-IL7R could inhibit the tumor growth in vivo and decrease the expression of Ki67." (PMID 29720427, 2018). "We found that higher Lnc-IL7R level corresponded to lower TNF-α level in tumor tissues." (PMID 29720427, 2018). "Furthermore, inhibition of Lnc-IL7R in vivo significantly restricted the tumor growth with decreased expressions of proliferation index Ki-67 and Lnc-IL7R." (PMID 29720427, 2018). "Thus, IL-7R signaling promotes survival and tumor aggressiveness of both malignant lymphoid and metastatic solid tumor cells." (PMID 28878234, 2017). "Forced-expression of IL-7R may therefore represent another strategy to overcome the T cell suppression imposed by continuous presentation of tumor antigen by immature myeloid cells." (PMID 29272267, 2017).
tumor (continued). "IL-7Rα expression in OVA-CD8+ T cells was statistically higher in tumor-bearing mice by day 30, but may be a result of IL-7Rαlow CD8+ T cells trafficking to the tumor site to exert effector functions." (PMID 29072624, 2017). "As IL-7R expression and signaling influenced tumor growth and resistance to steroids, we hypothesized that a therapy targeting IL-7R might be effective against such refractory malignant cells." (PMID 28878234, 2017). "In addition, the drop/rebound IL-7Rα expression pattern in tumor-specific CD4+ T cells is likely driven by TCR signaling alone." (PMID 28939858, 2017). "Although nuclear phospho-p63/NF-κB was inhibited in all IL-7R-KD cells, we considered the NF-κB pathway to be associated with tumor growth rather than steroid-resistance." (PMID 28878234, 2017). "However, there was a significant reduction of Ifngr1−/− or Il7r−/− T-cell infiltration into tumours, with the latter being more severe, which prevented further analysis of how IL-7Rα deficiency affects intratumoral T-cell effector function and Treg abundance." (PMID 27498556, 2016). "Combination treatment increases IL-7Rα expression on tumour-infiltrating T cells in an IFN-γ/IFN-γR signalling-dependent manner, which may serve as a potential biomarker for clinical trials with immune checkpoint blockade." (PMID 27498556, 2016). "Additionally, evidence suggests that IL-7R or/and IL-7 play an important role in tumor development and progression." (PMID 27821177, 2016). "Because the role of IL-7δ5 is also dependent on the interaction with IL-7R, it is possible that IL-7R may contribute to the EMT of tumor cells." (PMID 27821177, 2016). "The major goal of our study was to clarify whether and how host IL-7R signaling contributes to rIL-7-driven anti-tumor CD8+ T cell responses." (PMID 27447484, 2016). "After rIL-7 therapy only 1/12 Rag-/-IL-7R-/- mice remained tumor free." (PMID 27447484, 2016). "IL-7R was mainly found in the cytoplasm of tumor cells and adjacent tissues." (PMID 27821177, 2016). "Whether IL-7R should be detected in tumor sample before IL-7 administration will require further research." (PMID 25955647, 2015). "In contrast, regulatory/suppressor T cells (Treg), characterized ex vivo by high expression of the IL-2R α-chain (CD25) and of the lineage-specific transcription factor FOXP3 and low expression of the IL-7R α-chain (CD127), are believed to inhibit anti-tumor responses." (PMID 21829534, 2011). "In addition, the cytokine receptors IL4R and IL7R were found to be higher expressed in VEGFA165 tumours implicating the possibility of paracrine effects." (PMID 22045186, 2011). "Since IL7R signaling exerts its pro-tumor effects not only by promoting tumor cell proliferation and invasion but also by driving the polarization of immunosuppressive TAMs, combining IL7R inhibition with strategies that reprogram TAMs may enhance therapeutic efficacy." (PMID 41360767, 2025). "Additionally, tumor cells in these regions upregulated genes such as IL7R, CD80, and NLRC5, which are involved in T cell survival, co-stimulatory signaling, and antigen presentation, thereby supporting T cell recruitment, activation, and sustained immune responses." (PMID 41001043, 2025). "The association of IL7R expression after 3 doses of tebentafusp (but not prior to initiation of tebentafusp) with tumor reduction and OS suggests that recently recruited naive cells are key mediators of the anti-tumor activity of tebentafusp." (PMID 40239619, 2025). "However, considering the hypothesis of tumor immune surveillance, it is reasonable that the IL-7R level in T cells is elevated in the early period of PDAC." (PMID 37165046, 2023). "Therefore, our results demonstrated that CD8 + T cells with CCR7 + and IL7R + had the characteristics of malignant and immune cells, which could lead to tumor progression and immunosuppression." (PMID 37221625, 2023). "We next sought to investigate whether IL-7R was expressed on tumor antigen-specific T cells." (PMID 37459511, 2023).
tumor (continued). "New clonotypes appearing in blood or tumor at disease progression were enriched for genes associated with cytotoxicity or stemness (FGFBP2, GNLY, GZMH, GZMK, IL7R, SELL and KLF2), and these might be harnessed for alternative cellular therapy or cytokine therapy." (PMID 36514045, 2022). "In addition, we revealed that LINC01857, LINC02446, and LINC02384, as competing endogenous RNAs (ceRNAs) of IL2RA and IL7R, were oncogenes, while miR‐203b‐3p and miR‐891a‐5p, as microRNA sponges of IL2RA and IL7R, respectively, act as potential tumor suppressor molecules." (PMID 34159752, 2021). "CXCL12 and IL7R may be used as a new therapeutic target to study how different immune microenvironments affect cancer pathogenesis and how these genes regulate the interaction between different immune cells and the tumor microenvironment." (PMID 33344233, 2020). "Next we studied whether impaired tumor rejection in Rag-/-IL-7R-/- mice resulted from reduced LIP." (PMID 27447484, 2016). "However, tumor rejection strictly requires host IL-7R expression." (PMID 27447484, 2016). "In addition, our microarray data showed that (human) IL7R was upregulated in the VEGFA165 tumours." (PMID 22045186, 2011). "Our flow cytometric analysis showed differential expression of IL7R, CD40L, PD1, ICOS and HLA-DR between tumor Tfh-like subsets defined based on CD49f and CD103 expression within the CD4+ gate." (PMID 41542042, 2026). "Explainable AI then identified the top 10 transcripts whose abundance was predictive of tumour-reactive T cells including CXCL13, ANXA1, IL-7R, and TPT1, although the broad applicability of this approach in diverse cancer types still needs to be explored." (PMID 40801654, 2025). "Single-cell transcriptome sequencing revealed that IL-7R knockout enhanced the infiltration of mature B cells, CD8+ T cells, and macrophages into mice tumor tissues." (PMID 41360767, 2025). "Further, tumor-infiltrated T cells showed a significant downregulation of CD127, which is a sign of active T cells as effector T lymphocytes downregulate IL-7R expression after activation." (PMID 41221283, 2025). "Among potential biomarkers, the interleukin-7 receptor (IL7R) has gained attention for its role in immune regulation and tumor progression, indicating its promise in the ongoing search for effective treatment strategies." (PMID 40165301, 2025). "Normal tissues exhibited higher levels of S100A9, FTCD, POF1B, IL7R, and MYO1E, whereas tumor tissues showed increased expressions of SPINK1, CXCL9, AGFG1, and IQGAP3." (PMID 41578779, 2025). "We found that in the Il7r-regulated TME, tumor cells exhibited stronger interactions with macrophages than with CD8+ T or B cells." (PMID 41360767, 2025). "BayeSpace‐enhanced spatial data revealed the abundant infiltration of T cells (CD3D, IL7R), B cells (MS4A1, MZB1), and cytotoxicity markers (GZMK) throughout tumor sections of HT samples, presenting an “immune‐activation” TME after HAIC therapy." (PMID 39686623, 2025). "For example, it has been observed that FOXP1 inhibits the expression of the interleukin-7 (IL-7) receptor α chain (IL-7Rα) in CD8 + T cells and phosphorylates MEK and ERK to exert an anti-tumor effect." (PMID 38279090, 2024). "In summary, we present Lrp10 as a new determinant of IL7R expression in T cells that has important implications for CD8 T-cell fate decisions during normal homeostasis and anti-tumor immune responses." (PMID 38956225, 2024). "However, it is important to note that IL-7/IL-7R-mediated signaling may exert pro-tumor functions." (PMID 38424167, 2024). "We have also demonstrated infiltration of CD45, Macrophages, and NK cells into the tumor stroma, and upregulation of KLRG1, Sell, Ccr7, and IL7r upon the treatment with ICG-001 and then CAR Ts." (PMID 38449858, 2024). "This dataset was generated using the Tumor Immune Single Cell Hub (TISCH), and IL7R expression was superimposed on major cell lineages." (PMID 38554147, 2024).
tumor (continued). "Collectively, these data confirm that dex-mediated IL-7Rα upregulation on CAR T cells increases their responsiveness to IL-7, which allows for CAR T cells to have improved anti-tumor activity in the presence of IL-7." (PMID 38140726, 2024). "IL-7Rα and KLRG-1 surface markers were used to differentiate the two stages of T cell differentiation at the effector phase of the anti-tumor response: short-lived effector cells (SLECs) and memory precursor effector cells (MPECs)." (PMID 37033927, 2023). "A substantial part of these KLRK1+ CD8+ T cells, especially in the tumor, were bona fide KILR cells as shown by their high expression of IL-7R and GZMB and low expression of CD49d." (PMID 36705564, 2023). "The expression levels of IL7R, CD69, and PTPRC and the TNM stages of the tumor were significantly related to the OS rate of SKCM patients." (PMID 36032150, 2022). "IL-7Rα expression is positively correlated to the overall and progression-free survival in patients with LUAD, and negatively correlated to tumor size." (PMID 36142322, 2022). "Early activated (pro-memory) CD8+ T cells expressed marker genes IL7R (cluster 5 in Paratumor) or XCL1 (cluster 1 in Tumor) while with low expression of activated makers such as HLA-DR." (PMID 33429363, 2021). "While the majority of these genes and pathways are pro-immune and pro-apoptotic it is noted that several, such as MCL1, Bcl6, IL-7R, and SOCS are believed, in some situations to be immune regulatory and/or pro-tumor survival." (PMID 32757666, 2020). "CXCL12 and IL7R also exhibited significant differences in expression level between normal and tumor tissues (CXCL12: p = 4.47E-36; IL7R: p = 0.037), and between high and low ESTIMATE-scored groups (CXCL12: p = 6.26E-16; IL7R: p = 1.29E-09)." (PMID 33344233, 2020). "We found ten potential prognostic genes, including eight tumor suppressor and/or driver genes (VEGFA, CCND1, BAX, IL7R, SHC1, FLT1, IL7, and JAK3), as well as two chemokines (CXCL9 and CXCL10)." (PMID 31661791, 2019). "In comparison, tumor-specific CD8+ T cells in spleens, DLN and NDLN largely maintained IL-7R expression despite CD44 upregulation, and upregulation of CD69 was observed predominantly within the DLN." (PMID 31998326, 2019). "Taken together, the presence of CD8+PD-1+IL-7Rα−, CD4+PD-1+, and CD4+OX-40+ T cells indicates activated T cells in the tumor." (PMID 30042403, 2018). "Surface expression of CD62L and IL-7Rα was significantly higher in OVA-specific CD8+ T cells in the spleen and lymph nodes compared to the tumor." (PMID 29072624, 2017). "To circumvent chronic immune defects in Il7r−/− mice, we blocked IL-7 signalling in MB49 tumour-bearing mice before combination therapy." (PMID 27498556, 2016). "In summary, our data provide evidence for the complex interplay between IL-7R+ host and CD8+ T cells in the course of anti-tumor CD8+ T cell responses." (PMID 27447484, 2016). "Taken together, we conclude that combination therapy potently reverses immunosuppression and eradicates tumours via an intricate interplay between IFN-γ/IFN-γR and IL-7/IL-7R pathways." (PMID 27498556, 2016). "In summary, we provide evidence that host IL-7R signaling modulates multiple aspects of CD8+ T cells activation and TM differentiation and can promote tumor rejection in a context-dependent fashion." (PMID 27447484, 2016). "To test this, we adoptively transferred purified WT, Ifngr1−/− and Il7r−/− total T cells into sublethally irradiated CD45.1 mice, followed by tumour inoculation and combination therapy." (PMID 27498556, 2016).